GNAT3 (G protein subunit alpha transducin 3)
Description:
Guanine nucleotide-binding protein (G protein) alpha subunit playing a prominent role in bitter and sweet taste transduction as well as in umami (monosodium glutamate, monopotassium glutamate, and inosine monophosphate) taste transduction. Transduction by this alpha subunit involves coupling of specific cell-surface receptors with a cGMP-phosphodiesterase; Activation of phosphodiesterase lowers intracellular levels of cAMP and cGMP which may open a cyclic nucleotide-suppressible cation channel leading to influx of calcium, ultimately leading to release of neurotransmitter. Indeed, denatonium and strychnine induce transient reduction in cAMP and cGMP in taste tissue, whereas this decrease is inhibited by GNAT3 antibody. Gustducin heterotrimer transduces response to bitter and sweet compounds via regulation of phosphodiesterase for alpha subunit, as well as via activation of phospholipase C for beta and gamma subunits, with ultimate increase inositol trisphosphate and increase of intracellular Calcium. GNAT3 can functionally couple to taste receptors to transmit intracellular signal: receptor heterodimer TAS1R2/TAS1R3 senses sweetness and TAS1R1/TAS1R3 transduces umami taste, whereas the T2R family GPCRs such as TAS2R14 act as bitter sensors. Also functions as lumenal sugar sensors in the gut to control the expression of the Na+-glucose transporter SGLT1 in response to dietaty sugar, as well as the secretion of Glucagon-like peptide-1, GLP-1 and glucose-dependent insulinotropic polypeptide, GIP. Thus, may modulate the gut capacity to absorb sugars, with implications in malabsorption syndromes and diet-related disorders including diabetes and obesity.
Synonyms: gustducin; GDCA; HG1E
Tractability: Small molecule: a structure with a bound ligand is known. Antibody: its Gene Ontology location is reachable by antibodies, with high confidence. PROTAC: ubiquitination databases record sites on it.
Gene: Protein-coding gene on chromosome 7 (80,458,635 to 80,512,064, reverse strand). Ensembl gene ENSG00000214415.
Subcellular location: Cytoplasm
Subcellular location (Human Protein Atlas): Vesicles; Basal body
Pathways (Reactome):
Signal Transduction: Extra-nuclear estrogen signaling; G alpha (i) signalling events; G alpha (s) signalling events; G alpha (z) signalling events; GPER1 signaling
Disease: ADORA2B mediated anti-inflammatory cytokines production
Hemostasis: ADP signalling through P2Y purinoceptor 12
Metabolism of proteins: Synthesis, secretion, and inactivation of Glucagon-like Peptide-1 (GLP-1)
Neuronal System: Adenylate cyclase inhibitory pathway
Sensory Perception: Sensory perception of sweet, bitter, and umami (glutamate) taste
Gene Ontology:
Molecular function: G protein-coupled receptor binding; G-protein beta/gamma-subunit complex binding; GTP binding; GTPase activity; guanyl nucleotide binding
Biological process: adenylate cyclase-modulating G protein-coupled receptor signaling pathway; detection of light stimulus involved in visual perception; phototransduction, visible light; sensory perception of sweet taste; G protein-coupled receptor signaling pathway; response to nicotine; signal transduction
Cellular component: protein-containing complex; plasma membrane; acrosomal vesicle; apical plasma membrane; axoneme; cytoplasm; heterotrimeric G-protein complex; membrane
Genetic constraint (gnomAD): Loss-of-function variants: 8 observed, 14.3 expected, observed/expected ratio (o/e) 0.56, 90% interval 0.33 to 1.01. The upper end of that interval is the gene's LOEUF score, 1.01, which puts it in group 4 of 6, group 1 being the genes least tolerant of losing a copy. Missense variants: 142 observed, 155.94 expected, observed/expected ratio (o/e) 0.91, 90% interval 0.79 to 1.05. Synonymous variants: 43 observed, 50.46 expected, observed/expected ratio (o/e) 0.85, 90% interval 0.67 to 1.1.
Homologues: Orthologues: chimpanzee GNAT3 (100% identical), macaque GNAT3 (100% identical), dog GNAT3 (97% identical), rabbit GNAT3 (97% identical), pig GNAT3 (96% identical), rat Gnat3 (96% identical), mouse Gnat3 (95% identical), guinea pig GNAT3 (94% identical), Drosophila melanogaster Galphai (62% identical), Caenorhabditis elegans gpa-16 (56% identical), Caenorhabditis elegans gpa-4 (54% identical), Caenorhabditis elegans gpa-3 (46% identical), and 19 more. Paralogues in human: GNAT2 (80% identical), GNAT1 (78% identical), GNAI2 (69% identical), GNAI1 (68% identical), GNAI3 (68% identical), GNAO1 (62% identical), GNAZ (58% identical), GNA11 (50% identical), GNA14 (50% identical), GNAQ (49% identical), GNAL (44% identical), GNAS (44% identical), and 3 more.
Diseases named in the same sentence as GNAT3 in open-access papers:
GNAT3 is named in the same sentence as 29 diseases in open-access papers, as found by Europe PMC text mining. Sharing a sentence is not in itself a finding about the gene and the disease. The quoted sentences say what the papers report.
periodontitis (3 papers, 2019 to 2025). An acute or chronic inflammatory process that affects the tissues that surround and support the teeth. "As a result, we observed that salicin significantly alleviated periodontitis in WT mice with respect to gingival inflammation and alveolar bone loss, and this anti-periodontitis effects were significantly abolished in Gnat3-/- mice." (PMID 38605968, 2024). "To assess differences in proinflammatory cytokines associated with ligature-induced periodontitis, we measured the cytokine mRNA levels in gingiva from ligatured and unligatured molars in WT and Gnat3−/− mice." (PMID 31582750, 2019). "Gnat3‐deficient mice exhibit altered microbiota, increased alveolar bone loss, and more severe periodontitis, with an overgrowth of pathogenic Pasteurella, a pathogen associated with periodontitis." (PMID 40709685, 2025). "In mice, gingival SCCs express Tas2rs and signaling components of TAS2Rs, such as α‐gustducin (Gnat3), Trpm5, and PLCβ2, which help regulate oral microbiota and prevent periodontitis." (PMID 40709685, 2025). "Salicin treatment significantly inhibited the expression of CXCL1, CXCL2 and CXCL5 in the gingival tissue of WT-periodontitis mice, while these inhibitory effects of salicin were abolished in the Gnat3-/- periodontitis mice." (PMID 38605968, 2024). "Consistently, salicin-treatment inhibited periodontal bone loss, inflammatory/chemotactic factors expression, and neutrophil infiltration in periodontitis mice, while these effects were abolished in Gnat3−/− mice." (PMID 38605968, 2024). "The anti-inflammatory effects of salicin against LPS-induced MGFs were investigated in cell cultures, and were further validated with a ligature-induced periodontitis mouse model using Ga-gustducin-null (Gnat3−/−) mice." (PMID 38605968, 2024). "Consistent with results of our previous ligature experiments, after cohousing the Gnat3−/− mice developed more severe ligature-induced periodontitis than did WT mice, with an increased level of ABL and decreased bone volume per tissue volume (BV/TV)." (PMID 31582750, 2019). "Consistent with this, we found that a previously identified ligature-induced periodontitis-related commensal NI106015 was enriched in Gnat3−/− mice." (PMID 31582750, 2019). "MGF-specific Gnat3 knockout mouse are still needed to further explore the potential mechanisms in depth, and future clinical study is also needed to validate the effectiveness of salicin in the management of periodontitis." (PMID 38605968, 2024). "We further investigated whether Gnat3-knockout had impact on the anti-inflammatory effect of salicin on periodontitis." (PMID 38605968, 2024). "Activating Tas2r105 with denatonium benzoate in wild‐type mice was shown to upregulate antimicrobial β‐defensin‐3, reducing bone loss and bacterial load—an effect absent in Gnat3−/− mice, confirming the pathway's role, and thus the importance of Tas2r105 activation in regards to periodontitis." (PMID 40709685, 2025). "Our previous study induced periodontitis by tying silk ligatures around the left maxillary second molar of mice to maximize microbial colonization, as we hypothesized that Gnat3-/- mice harbored distinct microbiota that induced more severe periodontal bone loss." (PMID 38605968, 2024). "However, although slightly increased alveolar bone loss was observed in Gnat3–/– periodontitis mice as compared to WT mice in the current study, no statistical significance was observed." (PMID 38605968, 2024). "Mice lacking SCC taste signaling molecules (i.e., Gnat3−/− mice) or lacking SCCs (i.e., Pou2f3−/− mice) developed more severe ligature-induced periodontitis with an increased level of ABL compared with WT mice." (PMID 31582750, 2019). "Topical treatment with bitter denatonium to activate gSCCs upregulates the expression of antimicrobial peptides and ameliorates ligature-induced periodontitis in wild-type but not in Gnat3−/− mice." (PMID 31582750, 2019).
periodontitis (continued). "More importantly, topical application of salicin significantly suppressed neutrophil infiltration and alleviated periodontal destruction in WT mice rather than Gnat3-/- mice, further confirming the SCC-like activity of gingival fibroblasts in the development and resolution of periodontitis." (PMID 38605968, 2024).
dental caries (1 paper, 2023). The decay of a tooth, in which it becomes softened, discolored, and/or porous. "In preschool-aged children, SNP variants in TAS1R2 have beenassociated with dietary sugar intake and SNP variants in GNAT3 have beennominally associated with dental caries." (PMID 39076398, 2023).
metabolic syndrome (1 paper, 2014). A cluster of metabolic risk factors for CARDIOVASCULAR DISEASES and TYPE 2 DIABETES MELLITUS. "Although the term photoreceptor outer segment has no biological relevance to CRP or inflammation, the genes enriched in this pathway have biological relevance to CRP (HNF1A), high triglycerides (PCDH15) and metabolic syndrome (GNAT3)." (PMID 24763700, 2014).
Obesity (1 paper, 2020). Accumulation of substantial excess body fat. "Even though TAS1R3 and GNAT3 were not related to sweet perception in this review, a third sweet-related gene, TAS1R2, has been observed to be linked with sweet taste threshold and consumption of sweet food in individuals with obesity compared to individuals with normal weight." (PMID 32635385, 2020).
pneumonia (1 paper, 2025). An acute, acute and chronic, or chronic inflammation focally or diffusely affecting the lung parenchyma, caused by an infection in one or both of the lungs (by bacteria, viruses, fungi, or mycoplasma.). "Here, we investigated the role of TAS2R signaling in Staphylococcus aureus-induced murine pneumonia via wild-type (WT) and several mutants (mTas2r104-/-/105-/-, mTas2r105-/-/114-/-, mTas2r104-/-/105-/-/114-/-, Gnat3-/- and Gnat3-/–mTas2r104-/-/105-/-) mice." (PMID 41142782, 2025).
metabolic disorder (2 papers, 2020 to 2022). "Thus, hypothetically, the GNAT3 gene may affect the oral microbiota via dietary habits or secondary effects from diet-related metabolic disorders." (PMID 32138214, 2020).
tumor (2 papers, 2021 to 2022). "MAPK inhibition in NKX2-1-negative tumor cells was also associated with induction of several markers of chemosensory tuft cells, including the lineage specifier Pou2f3 as well as Gfi1b and Gnat3." (PMID 33821796, 2021).
infection (1 paper, 2025). The state of being infected such as from the introduction of a foreign agent such as serum, vaccine, antigenic substance or organism. "Infection-related induction of most chemokines was evident in both WT and mutant mice, but responses were significantly blunted in Gnat3-mTas2r104-/-/105-/- animals." (PMID 41142782, 2025).
GNAT3 also shares sentences with these, for which no sentence is quoted: cholangiocarcinoma (2 papers); cholestasis (2); liver fibrosis (2); Alzheimer disease (1); Anosmia (1); Anxiety (1); atherosclerosis (1); breast carcinoma (1); cancer (1); carotid atherosclerosis (1); colitis (1); diabetes (1); gastrointestinal tumors (1); glaucoma (1); hyperglycaemia (1); hyperlipidaemia (1); Infertility (1); kidney disease (1); liver cirrhosis (1); liver disease (1); lung carcinoma (1).